EGFR (epidermal growth factor receptor)
Diseases named in the same sentence as EGFR in open-access papers (continued):
Sharing a sentence is not in itself a finding about the gene and the disease.
tumor (continued). "Thus, in line with its well-characterized hyperactivity, EGFR-mutated tumor cells appear to carry alterations in their EV landscape, both in the subtype released and cargo selected." (PMID 33321449, 2021). "Taken together, these results demonstrate that somatic mutations, particularly EGFR mutations, were more likely to be detected in CSF samples than in plasma samples, indicating that CSF samples are the optimal tumor DNA source for molecular testing in patients with LM." (PMID 35127465, 2021). "However, efforts to target EGFR were associated with poor outcome in TNBC due to tumor heterogeneity and activation of alternative signaling pathways." (PMID 34638492, 2021). "Thus, our in vivo data largely reflects our in vitro findings and suggests that combination therapy is necessary to induce substantial tumor shrinkage in tumors harboring activating EGFR and BRAF mutations." (PMID 34921211, 2021). "Besides ETA, EGFR is also overexpressed in OC, being usually linked to poor prognosis and related to tumour resistance to chemotherapy, thus making it a prominent therapeutic target." (PMID 34367381, 2021). "Besides, wild-type EGFR associated with tumor cell invasion and angiogenesis has been demonstrated in several in vivo and in vitro experiments." (PMID 34394352, 2021). "Authors used a method to visualize tumor region that was most related to EGFR mutation status." (PMID 34026602, 2021). "The discordance of EGFR mutations between the two samples might have occurred if the number of tumor cells harboring EGFR mutations with mutations was too small to detect these mutations, due to heterogeneity in FFPE tumor sections by conventional PCR." (PMID 33757469, 2021). "Two tumor samples, T15 and T5, carried EGFR mutations and amplification." (PMID 34285259, 2021). "Lastly, it is important to note that the ctDNA concentrations in plasma are dependent on tumor burden, site of metastasis but also genotype and EGFR gene amplifications which might impair performance of the EGFR mutation detection form plasma." (PMID 33935776, 2021). "In 2004, two papers reported that the presence of an EGFR mutation appeared to be linked to dramatic tumor response with gefitinib, but the magnitude of that discovery was not realized, and the standard-of-care was for patients to be treated without biomarker selection." (PMID 33777559, 2021). "Furthermore, HER3-targeting patritumab deruxtecan, another ADC, exhibited impressive tumor shrinkage in pretreated patients with EGFR-mutated NSCLC, in a phase 1 clinical trial." (PMID 33801379, 2021). "In 51 patients who had uncommon EGFR mutations with comprehensive tumor genomic information, the multivariate analysis additionally identified that co-mutations of tumor-suppressor genes were also independently associated with poorer PFS (p = 0.001, HR 3.545, 95% CI 1.632–7.703)." (PMID 34513661, 2021). "Furthermore, it is well-established that EGFR is implicated in the regulation of cancer cell growth and tumor development." (PMID 33495409, 2021). "Besides, the concurrent presence of some SNPs of Aurora kinase A and EGFR mutation were related to an earlier tumor stage of LADC." (PMID 33799753, 2021). "The anticancer effects of AA on HCC were predicted to be associated with regulating tumor cell proliferation, apoptosis, angiogenesis, tumor invasion, and metastasis via various pathways such as EGFR signaling pathway, ESR1 signaling pathway, and CCND1 signaling pathway." (PMID 33688369, 2021). "[125I]ICO1686 could detect the EGFR with L858R/T790M double mutations in vitro; however, it showed insufficient tumor uptake and low tumor/blood ratio of radioactivity." (PMID 33809064, 2021). "In our study, EGFR is the predominant mutation in CSF, plasma, and tumor tissues." (PMID 34671549, 2021).
tumor (continued). "In fact, under the selective pressure of anti-EGFR MAbs, either a preexisting population of subclones carrying the resistance mutations can rapidly expand or de novo molecular resistance mutations can be developed, thus determining tumor progression." (PMID 33920531, 2021). "Relationship between the MF of EGFR T790M mutation and tumor response to osimertinib." (PMID 33131198, 2021). "Perhaps, EGFR mutations can be detectable in cfDNA when the tumor load is higher." (PMID 34680416, 2021). "Moreover, wild-type EGFR is overexpressed in 10% to 90% of NSCLC tumor tissues, whereas its activation mutation is only found in 10% of NSCLC patients." (PMID 34102455, 2021). "Notably, there was an identical mutation (including EGFR L858R mutation) in the two separated tumor lesions from patient 9 (P9)." (PMID 34109114, 2021). "The results showed that EGFR mutations were detected in 45.9% (50/109) of plasma samples and 56.9% (62/109) of matched tumor tissue samples and verified the sensitivity (82%), specificity (100%), positive predictive value (100%), and negative predictive value (81.4%) of SuperARMS." (PMID 32695166, 2020). "The stochastic coactivation of PI3K and MAPK/EGFR pathways promotes the formation and progression of this growth front causing the brain lobes to appear elongated and misshapen ultimately causing lethal neoplasms." (PMID 32457905, 2020). "The EGFR mutation test results between tumor tissue and plasma were compared." (PMID 32224854, 2020). "Interestingly, studies have shown that EGFR-mutated NSCLC tended to express PD-L1 on tumor cells at higher frequency, yet they benefit less from anti-PD1 therapies than wild-type tumors." (PMID 32085544, 2020). "EGFR mutation analysis of cftDNA extracted from baseline plasma was performed with the three methodologies (Scorpion-ARMS EGFR Plasma, PNAClamp R EGFR and QuantStudio 3D Digital PCR) and compared with the EGFR mutation analysis of the corresponding tumor tissue sample." (PMID 33297595, 2020). "Targeted therapies directed at tumour cells harbouring epidermal growth factor receptor (EGFR) gene mutations, anaplastic lymphoma kinase (ALK) gene rearrangements, ROS proto-oncogene 1 (ROS1) gene fusions, and B-Raf proto-oncogene (BRAF) gene mutations have produced impressive results." (PMID 32907572, 2020). "Age and tumor grade was significantly associated with EGFR expression." (PMID 33273921, 2020). "Besides, ciRS-7 can abrogate the tumor-suppressive effect of miR-7 via different cancer-associated signaling pathways including EGFR, PTEN/PI3K/AKT, NF-κB, and IGF1R." (PMID 32090067, 2020). "In addition, the dysregulation of EGFR signaling is associated with poor prognosis, rendering this receptor a potential target for anti-tumor treatment." (PMID 32839411, 2020). "Here, we report a novel EGFR L858R/A859S/Y891D triple mutation in plasma-derived circulating tumor DNA (ctDNA) was identified in a 53-year-old male patient with NSCLC resistant to osimertinib treatment, using an ultra-deep (20,000×) 160-gene panel through the NGS platform." (PMID 33324543, 2020). "In those confirmed with lung cancer by the diagnostic imaging and protein tumor markers but failure with the biopsy procedure, or inadequate tumor tissue for EGFR mutation analysis, clinical doctors should require the mutation testing in plasma before starting chemo-radiotherapy." (PMID 32746896, 2020). "Importantly, Formo is well-tolerated in vivo and exhibited no significant toxicity to vital organs, indicating that Formo is a potential anti-tumor candidate compound for EGFR WT and activating mutation NSCLC treatment." (PMID 32276600, 2020). "Moreover, JNJ-61186372 downregulated receptor expression on tumor cells thus preventing the drug resistance mediated by new emerging mutations of EGFR or c-MET." (PMID 32989604, 2020). "It has been reported that there were associations between EGFR expression, tumor grade, and stage." (PMID 32795296, 2020).
tumor (continued). "This allowed the metastatic carcinoma patients individuation with accuracy between 84% and 96% and identified surrogate signatures of spliced RNAs, associated with the molecular subtype of the tumor tissue, such as EGFR and KRAS mutations and HER2 and MET amplification." (PMID 36046776, 2020). "Therefore, the identification of RAS mutations in tumor tissues to determine patients that are more likely to benefit from anti-EGFR therapies has become standard of care." (PMID 32231042, 2020). "Thus, gene amplification, and particularly EGFR gene amplification, is currently considered a major driver of tumor progression with potential prognostic value for risk stratification of GBM." (PMID 31963499, 2020). "The AUC for detecting tumor EGFR mutations using the plasma samples was 0.686 (95% CI: 0.592–0.780), whereas that using the BWF samples was 0.895 (95% CI: 0.822–0.969), showing a significant difference between the types of specimens (p < 0.0001; DeLong’s test for two correlated ROC curves)." (PMID 32517757, 2020). "Dimerization causes EGFR autophosphorylation at specific tyrosine residues in its intracellular domain, triggering downstream signaling pathways that are often overactivated in malignant cells during tumor progression." (PMID 31936715, 2020). "These are decorin, which binds with high affinity to the EGFR, causing downregulation of kinase activity and blocking intracellular calcium mobilization and thereby acting as tumor suppressor, tenascin C, the γ2 chain of laminin-332, thrombospondin-1 and fibulin-3." (PMID 32796709, 2020). "CTCs can detect mutations in the EGFR gene accurately and could solve the problem of obtaining tumor tissue in clinical settings." (PMID 32856417, 2020). "Collectively, these data support the role of FcγR interactions in the major off-tumor toxicities associated with IgG-based 4-1BB agonists and further validate the safety profile of EGFR-targeted Fc-less 4-1BB-agonistic trimerbodies in systemic cancer immunotherapy protocols." (PMID 33488625, 2020). "Interestingly, even with a mixed SCLC and NSCLC phenotype, the transdifferentiated SCLC tumour retained their original EGFR mutation, indicating that they were notde novo tumours." (PMID 32595946, 2020). "Here, the elastic net (with 5-fold nested cross-validation) finally selected nine features including smoking, pathology, location, EGFR mutation status, age, tumor diameter, clinical N stage, consolidation chemotherapy and radiation dose to build prediction model." (PMID 32070383, 2020). "Despite these preliminary evidence, the exact relevance of CD73-adenosine signaling in both EGFR-mutated tumor cells and infiltrating immune cells to the efficacy of immune checkpoint inhibitors remains unclear." (PMID 32760402, 2020). "Loss of tumor suppressor genes may enable these tumor cells to reexpress developmental TFs and to exhibit cell plasticity under selective pressure of potent AR inhibition (prostate) or EGFR inhibition (NSCLC)." (PMID 33297508, 2020). "Recently, some studies have shown that EGFR inhibitors may exhibit anti-tumor effects, which are associated with the continued promotion of reactive oxygen species production and induction of apoptosis." (PMID 32068233, 2020). "The loss of coupling between normal integrin and EGF receptor (EGFR) signaling may be further cause for anoikis resistance in tumor cells." (PMID 32033410, 2020). "Such strategies, or ‘liquid biopsies’, already have value in lung neoplasia, e.g. for monitoring treatment responses to epidermal growth factor receptor (EGFR) inhibitors through identification of mutation T790M in circulating tumour DNA, and are becoming standards of care." (PMID 32047924, 2020). "Sel-Cap showed very high sensitivity (88%) for EGFR resistance mutation T790M in plasma samples, and among the 85 plasma samples tested, Sel-Cap identified 14 more T790M-positive samples which the PNAclamp tumor biopsy was unable to detect." (PMID 33266057, 2020).
tumor (continued). "Since our IPM is based on tumor microenvironment-related genes, although its establishment is related to EGFR mutation, ALK translocation, ROS1 translocation, and BRAF mutation, it is applicable to all patients with or without these mutations in stage I-II LUAD." (PMID 33585210, 2020). "However, it remains confused that what components in a mixed LAC tumor are responsible to the heterogeneous EGFR mutation and PD-L1 expression." (PMID 32093629, 2020). "Therefore, we excluded the patients with the presence of EGFR-sensitive gene mutation in tumor tissue." (PMID 32043180, 2020). "Our results may suggest various clinical applications to overcome EMT associated EGFR-TKIs resistance due to tumor heterogeneity." (PMID 33287368, 2020). "In a previous study, we have shown for the first time that NSCLC patients carrying EGFR mutations in tumor tissue and subjected to first-line treatment with EGFR TKIs, can be strictly monitored in the first days of treatment by repeated blood draws to quantify EGFR mutant alleles in plasma." (PMID 32215186, 2020). "These suggest that elevated EGFR is associated with tumor aggressiveness." (PMID 32093644, 2020). "In subgroup analysis among EGFR mutated adenocarcinoma, ctDNA was significantly associated with nodal metastasis, vascular invasion, solid adenocarcinoma pattern, and tumor necrosis, high mitotic rate, large pathological tumor size, and large tumor volume on CT." (PMID 32196518, 2020). "Several tumor-associated mutations of the EGFR gene have been identified." (PMID 32391048, 2020). "Therefore, a better understanding of biological mechanisms involved in tumor progression and immune evasion as well as of the dynamic hallmarks of EGFR-mutated NSCLC TME is required." (PMID 32760402, 2020). "The results presented in this study are the first demonstration that CMTM5 loss and EGFR deregulation are observed in PCa cells, which provides a crucial signaling platform required for androgen-independent tumor transition and progression and for the malignant behavior of tumor cells." (PMID 32328181, 2020). "Tumor tissues of all patients were tested for EGFR mutation status." (PMID 33134170, 2020). "Only EGFR gain-of-function alterations, including amplification, may be associated with the anti-tumor effect of GC1118." (PMID 33142709, 2020). "Therefore, confirmation experiments using clinical materials containing tumor cells with EGFR mutations in sputum are necessary." (PMID 32033355, 2020). "In addition, the NIC in the AP and VP and λHU in the VP had higher values in the EGFR-mutated tumours than in the EGFR wild-type tumours." (PMID 32103127, 2020). "SNARE-dependent association of β1-integrin and EGFR association can regulate invadopodia formation and tumor cell invasion in a process that might be driven, in part, by EV-mediated mechanisms." (PMID 32978434, 2020). "Ultimately, we compared the results of this combined liquid biopsy to the tumor tissue biopsy when available, in order to further investigate the feasibility of using non-invasive EGFR mutation analysis as a potential tool for monitoring treatment and medication guidance of NSCLC patients." (PMID 33117705, 2020). "We speculate that it may be caused by the following reasons.The electric field affects different ion channels of different tumor cells, which may cause EGFR to play different roles when EF stimulates various types of tumor cells." (PMID 32210363, 2020). "An alternative explanation may be that EGFR mutated tumors tend to have more tumor cell “spillage” during or prior to surgery, as indicated in prior studies, which in turn results in increased rates of metastatic recurrence." (PMID 32523650, 2020). "Here, we addressed the issue by proposing a combinatorial approach targeting two different tumor-associated antigens (EpCAM and EGFR) with a bivalent bispecific antibody and multivalent costimulatory antibody-fusion proteins with affinities in the lower nanomolar range, respectively." (PMID 32504247, 2020).
tumor (continued). "EGFR mutations identified in blood circulating cell-free DNA (cfDNA) have been shown to similarly predict response to EGFR tyrosine kinase inhibitors in the 1L and 2L treatments of mNSCLC with comparable accuracy to mutations identified via tumor tissue biopsy." (PMID 32599934, 2020). "However, PD-1/PD-L1 inhibitors lack efficacy in most NSCLC patients with EGFR mutations, even in those with high PD-L1 expression (tumor proportion score [TPS] ≥50%)." (PMID 33363040, 2020). "Subgroup analyses were performed regarding EGFR mutation type, tumor stage, and EGFR-TKI treatment." (PMID 32195189, 2020). "In a TATTON study, a phase Ib trial, MET-amplified, and EGFR-mutant patients were treated with osimertinib plus savolitinib showing an acceptable risk-benefit profile and encouraging anti-tumor activity of the combination (objective partial responses in 48% of patients)." (PMID 32397295, 2020). "According to the results of the tumor tissue EGFR analysis, twenty patients (64.5%) had Del 19 mutation, six patients (19.4%) had L858R mutation, one (3.2%) had both L858R and T790M mutations and four (12.9%) had other mutations (G719S+L833V, L861Q, L858M, G719C, and S768I)." (PMID 33297595, 2020). "Finally, we described the rate of EGFR-T790M resistance mutations detected in circulating tumor DNA (ctDNA) after treatment with TKI in a group of patients." (PMID 32714871, 2020). "Importantly, the concordance for ALK and EGFR mutations across 18 patients was 100%, showing that tumor exosomes derived from pleural fluid can be used to guide treatment with targeted agents." (PMID 33139621, 2020). "EGFR mutations are usually accompanied with prolonged signaling that is associated with metastasis, angiogenesis, apoptosis inhibition, and enhanced proliferation of the tumor cells." (PMID 32391048, 2020). "RAB proteins are an indispensable component of the membrane trafficking system that controls secretion, transport, recycling, and degradation of many tumor-associated proteins such as beta-integrins, epidermal growth factor receptor (EGFR), and matrix metalloproteinases (MMPs), among several others." (PMID 32759795, 2020). "In subgroup analysis, detection of EGFR mutated ctDNA was significantly associated with nodal metastasis (p = 0.029), vascular invasion (p = 0.029), solid adenocarcinoma pattern (p = 0.010), and tumor necrosis (p = 0.010) of primary tumor." (PMID 32196518, 2020). "Blood samples from 24 NSCLC patients and 6 age-matched healthy donors were analyzed with this combined workflow to minimize blood volume needed and sample-to-sample bias, and the EGFR mutation profile detected from CTCs and cfDNA was compared to matched tumor tissues." (PMID 33117705, 2020). "Two tumors (17%) had EGFR amplifications and 1 tumor (8%) had an IDH1 R132H mutation." (PMID 33063013, 2020). "We will exploratorily analyze the relationships of the blood concentration of osimertinib with its efficacy against brain metastasis of NSCLC and the accumulation of osimertinib in cerebrospinal fluid and evaluate tumor-derived DNA from plasma specimens for mutations in EGFR and other genes." (PMID 32357848, 2020). "Interestingly, psid mutation significantly inhibited activated EGFR-induced tumor growth in both regions (Yellow and white arrowheads, tumor cells were marked by GFP)." (PMID 32559195, 2020). "An important example of blood-based LBx clinical utility is the assessment of epidermal growth factor receptor (EGFR) mutations in circulating tumor DNA to guide the use of EGFR tyrosine kinase inhibitors in patients with advanced-stage non-small-cell lung carcinoma." (PMID 32366915, 2020). "Despite the small number of cases, their results indicated that the early reduction in the FDG uptake in the tumor mass after initiation of molecular agents could predict the subsequent tumor response in patients with EGFR-mutated or ALK-rearranged NSCLC." (PMID 33182575, 2020).